MYD88 (MYD88 innate immune signal transduction adaptor)
Diseases named in the same sentence as MYD88 in open-access papers (continued):
Sharing a sentence is not in itself a finding about the gene and the disease.
encephalitis (6 papers, 2013 to 2025). An acute inflammatory process affecting the brain parenchyma. "The data demonstrate highly increased susceptibility of MyD88−/− mice to Toxoplasma-induced encephalitis, which is correlated with reduced innate and adaptive immune responses." (PMID 23374751, 2013). "For instance, absence of TLR responses for deficiency in the TLR adaptor proteins MyD88 (myeloid differentiation primary response 88) or TRIF (TIR-domain-containing adapter-inducing interferon-β) results in encephalitis and host death following HSV-1 infection." (PMID 30254622, 2018). "However, MyD88−/− mice compared to MyD88+/+ mice were highly susceptible to cerebral infection, displayed high parasite migration to the brain, severe neuropathological signs of encephalitis and succumbed within 2 weeks of oral infection." (PMID 23374751, 2013). "It highlights genetic defects such as deficiencies in MyD88, IRAK-4, NEMO, and TLR3, which lead to distinct clinical phenotypes, for example, increased susceptibility to bacterial infections or herpes simplex virus type-1 (HSV-1) encephalitis." (PMID 41369391, 2025). "Importantly, upon MAVS deletion we did not detect impaired infiltration with CD8+ T cells, further supporting the concept that MyD88-dependent chemokine responses drive T-cell infiltration during viral encephalitis." (PMID 40619428, 2025). "Moreover, it was demonstrated that the adaptor molecule MyD88 or the TLR2 and TLR9 receptors together are crucial to host survival, since mice deficient in these molecules succumb to HSV-1 infection with encephalitis, whereas wild-type (WT) C57BL/6 mice can control the infection and survive." (PMID 28222752, 2017). "Studies have shown that deficiency in some TLRs and their transducers, such as MyD88 (myeloid differentiation primary response 88) and TRIF (TIR-domain-containing adapter-inducing interferon-β), can result in encephalitis and host death." (PMID 28222752, 2017). "We report that the absence of MyD88 signaling impacts host defenses and is essential for protection during the acute stage of encephalitis of T. gondii infection as MyD88−/− mice succumbed to Toxoplasma encephalitis." (PMID 23374751, 2013).
endometriosis (6 papers, 2019 to 2023). The growth of functional endometrial tissue in anatomic sites outside the uterine body. "Immunohistochemical analysis of endometriotic tissues showed that TLR3, TLR4, and MYD88 were localized in endometriosis lesions." (PMID 36093086, 2022). "The antagonist of TLR4 (LPS-RS-Ultra, LRU) and MyD88 homodimerization inhibitory peptide (MIP) were intrathecally administrated to assess the behavioral effects of blocking TLR4 signaling on endometriosis-related pain." (PMID 33673857, 2021). "Because LPS binds to TLR4 and activates MyD88 signaling, the current findings using Myd88−/− mice are consistent with LPS actions in endometriosis." (PMID 31507610, 2019). "Furthermore, we demonstrated that neutralizing antibodies to IL-33 and/or IL-1R1, or an inhibitor of IRAK4 (involved in MyD88 signaling) were effective for the treatment of endometriosis in this model." (PMID 31507610, 2019). "We investigated the role of IL-33, IL-1R1, and MyD88 in the development of endometriosis in mice, and demonstrated the potential of inhibitors for IL-1/IL-33 and their signaling pathway as therapeutic targets for endometriosis." (PMID 31507610, 2019). "Because the signal transduction pathway mediated by MyD88 was essential for endometriosis lesion formation, we investigated whether inhibition of IRAK4 (an essential protein kinase for this pathway) provided an effective treatment." (PMID 31507610, 2019). "Blockade of TLR4 and MyD88 might serve as a potential treatment for pain in endometriosis." (PMID 33673857, 2021). "Therefore, it is possible that blocking the MyD88 signaling pathway may provide an effective treatment for endometriosis." (PMID 31507610, 2019). "Therefore, we investigated the formation of endometriosis-like lesions in MyD88-deficient mice lacking the key signaling pathway of IL-1 family cytokines." (PMID 31507610, 2019). "MYD88, NF-ĸB, IL-10, and TGF-β showed a significantly higher expression in endometriosis patients compared to the control (p<0.05)." (PMID 33209739, 2020). "Also, endometriosis upregulated the expression of TLR4 and Myd88 in small-diameter nociceptors with increased phosphorylation of NF-κB in the DRG." (PMID 33673857, 2021).
hyperlipidemia (6 papers, 2016 to 2025). "Moreover, when the participants had hyperlipidemia, the OR (95% CI) was 3.269 (1.398–7.644) between TLR4 rs11536889 and MyD88 rs7744 (p value for interaction = 0.006)." (PMID 26959040, 2016). "In addition to proinflammatory cytokines, high-fat diet (HFD)-induced hyperlipidemia also enhances PCSK9 expression potentially by modulating Toll-like receptor (TLR) 4 and its downstream signaling factors myeloid differentiation primary response gene 88 (MyD88) and nuclear factor kappa-B (NF-κB)." (PMID 39963241, 2025).
Lyme borreliosis (6 papers, 2011 to 2023). "We can use similar techniques to look at the role of the macrophage response and MyD88 signaling in human macrophages, with the goal of increasing our understanding of the clinical spectrum associated with Lyme disease pathogenesis." (PMID 34000990, 2021). "A similar reliance on TLR/MyD88-dependent responses for pathogen clearance may explain the effects of complement component C3 deficiency on the course of murine Lyme borreliosis." (PMID 24967215, 2014). "The role of MyD88 in experimental Lyme disease, but also in the host response against B. burgdorferi was studied previously." (PMID 23148704, 2012). "Thus, MyD88-dependent innate signaling is not driving the induction of lymphadenopathy, nor the massive activation of B cell responses associated with Lyme borreliosis." (PMID 21637808, 2011). "Previous studies showed that γδ T cell activation in response to Borrelia burgdorferi infection in a TLR2-dependent manner, suggesting an involvement of MyD88 signaling during in vivo activation." (PMID 25232836, 2014). "Interestingly, a recent in vitro study of neuroborreliosis, using human brain microvascular endothelial cells challenged with Borrelia bavariensis, also showed an upregulation of IRAK2 and MYD88, while no significant changes were detected for IRAK1 or TRAF6 expression." (PMID 37319241, 2023).
meningitis (6 papers, 2011 to 2025). A disorder characterized by acute inflammation of the meninges of the brain and/or spinal cord. "Data from two-way ANOVA indicated significant interactions between the variables (MyD88 and meningitis) on weight loss [F = 8.687, p < 0.01] and clinical scores [F = 5.345, p = 0.027]." (PMID 28615695, 2017). "IRAK4- or MYD88-deficient patients are predisposed to recurrent invasive infections with S. pneumoniae, especially meningitis." (PMID 22996269, 2013). "The robust acute meningitis phenotype observed in Myd88-deficient mice, characterized by an impaired host immune response and reduced brain pathology compared with infected WT mice, suggests that TLRs play a crucial role in eliciting the immune response to pneumococcal CNS infection." (PMID 38358825, 2024). "Two-way ANOVA indicated interactions significant between the variables (MyD88 and meningitis) on these inflammatory mediator productions (except expression of IL-10 in cortex)." (PMID 28615695, 2017). "Data from two-way ANOVA indicated significant interactions between MyD88 and meningitis on BDNF expression." (PMID 28615695, 2017). "Two-way ANOVA indicated significant interactions between the variables (MyD88 and meningitis) on hippocampal apoptosis [F = 8.089, p = 0.015]." (PMID 28615695, 2017). "Here TLR4 WT (C3H/FeJ) and TLR4 mutant (C3H/HeJ) mice as well as MyD88 KO animals were infected intracerebrally with live C. koseri, resulting in meningitis and ventriculitis with accompanying brain abscess formation." (PMID 21496301, 2011). "To evaluate the functional importance of MyD88-dependent pathways for CNS immune responses to C. koseri, we employed a mouse model of meningitis and brain abscess formation using a C. koseri clinical isolate." (PMID 21496301, 2011). "Strikingly, the meningitis phenotype of Tlr2–/– Tlr4–/– (Tlr2/4–/–) double-knockout (double-KO) mice was stronger than that of Tlr2–/– mice, yet significantly milder than that of Myd88–/– mice." (PMID 38358825, 2024). "However, in the spleens, interactions were identified between MyD88 and meningitis [F = 35.366, p < 0.01]." (PMID 28615695, 2017). "Also, the MyD88-deficient animals could not prevent E. coli K1 neonatal meningitis, showing that MyD88 plays an essential role in early host defense." (PMID 36864913, 2023). "In this study, we aimed to investigate if activation of the classical inflammatory signaling pathway, namely the MyD88/NF-κB signaling pathway, regulates BDNF expression in experimental S. pneumoniae meningitis." (PMID 28615695, 2017).
Myocardial fibrosis (6 papers, 2021 to 2024). "Together, these findings in the present study indicate that LQF alleviated myocardial fibrosis owing to inhibiting TLR4/MyD88/NF-κB signaling pathway and inhibited NLRP3 inflammasome activation." (PMID 35310035, 2022). "MGIIIE plays a role in anti-myocardial fibrosis, by inhibiting TLR4/MyD88/NF-κB signaling expression, and decreasing inflammatory cytokine release." (PMID 36594066, 2023). "We demonstrated that LQF can efficiently inhibit TLR4/MyD88/NF-κB signaling pathway activation and thereby inhibit NLRP3 inflammasome activation and alleviate myocardial fibrosis in MI mice." (PMID 35310035, 2022). "In conclusion, LQF may downregulate TLR4/MyD88/NF-κB pathway and inhibit the activation of NLRP3 inflammasome, thereby reducing inflammatory response and myocardial fibrosis." (PMID 35310035, 2022).
silicosis (6 papers, 2014 to 2025). Silicosis is a respiratory disease caused by breathing in (inhaling) silica dust. "In summary, CHRF may exacerbate inflammation and fibrosis associated with silicosis through the miR-489/MyD88/Smad3 pathway." (PMID 40612103, 2025). "Our study demonstrates that the MyD88-signaling pathway mobilized during the lung responses to silica particles organizes granuloma formation, Th17-associated inflammatory responses and neutrophil accumulation; three major features of silicosis." (PMID 25050810, 2014). "These authors found a significant reduction of lung inflammation and granuloma formation in MyD88-KO mice after silica, giving support to the interpretation that MyD88-related innate immunity is crucial in silicosis." (PMID 27014274, 2016). "miR-489 may indirectly inhibit IL-1β and TGF-β1 by regulating MyD88, alleviating the inflammatory process of silicosis." (PMID 40612103, 2025). "In non-small cell lung cancer and silicosis, CHRF exacerbates inflammation and fibrosis via the miR-489/MyD88/Smad3 axis." (PMID 40612103, 2025). "Notably, the expression of myeloid differentiation factor 88 (MyD88) and toll-like receptor adaptor molecule 1 (TLRAM1) elevate in AMs of humans treated with LPS, indicating that LPS-regulated autophagy may be dependent on TLR4-MyD88 or TLR4-TLRAM1 signaling pathway in human silicosis." (PMID 33466366, 2021).
skin infection (6 papers, 2015 to 2021). An inflammatory process affecting the skin, caused by bacteria, viruses, parasites, or fungi. "A skin infection model using MyD88-deficient mice found that these mice had a reduced capacity for neutrophil recruitment and cytokine production, resulting in increased susceptibility to infection." (PMID 26901227, 2016). "Whether LTB4/MyD88 axis regulates abscess formation during MRSA skin infection remains to be investigated." (PMID 30102746, 2018). "Corroborating in vitro data, Myd88−/− knockout mice downregulated TNF, CXCL1; and phospho-p65 and phospho-IRF3 nuclear localization, upon poly I:C treatment in a mouse model of skin infection." (PMID 32824595, 2020).
Thrombocytopenia (6 papers, 2013 to 2025). A reduction in the number of circulating thrombocytes. "The observation that anti-platelet antibody resulted in thrombocytopenia in Myd88 deficient mice suggests that, similar to TLR4, Myd88 expression is not required for the induction of thrombocytopenia in the murine ITP model." (PMID 23940791, 2013). "Pretreatment of Myd88 deficient mice with IVIg protected against thrombocytopenia (column 7)." (PMID 23940791, 2013). "Compared with that in the control group, the expression of TLR7, MyD88, IRAK4, and TRAF6 increased significantly in the B cells of patients with pSS associated thrombocytopenia (p < 0.05)." (PMID 33767707, 2021). "LPS usually signals via MyD88, however lack of platelet MyD88 did not alter host responses to LPS including thrombocytopenia and immune cell recruitment." (PMID 31379873, 2019). "LPS can also induce thrombocytopenia, potentially through LPS interaction with the TLR4/Myd88 signaling pathway, and platelet aggregation may play a role in this process." (PMID 23940791, 2013).
acute myeloid leukemia (5 papers, 2020 to 2025). Acute myeloid leukemia (AML) is a group of neoplasms arising from precursor cells committed to the myeloid cell-line differentiation. "Notably, the MyD88 pathway emerged as a critical component, influencing prognosis in acute myeloid leukemia and guiding innovative immunotherapies." (PMID 40922674, 2025). "Additionally, acute myeloid leukemia (AML) cells uptake exogenous palmitate via CD36, activating ZDHHC6-mediated MYD88 palmitoylation to potentiate the TLR4-LYN-MYD88-NF-κB signaling axis." (PMID 40977744, 2025). "In the mouse model of acute myeloid leukemia (AML), IFN-γ receptor 1 (IFNGR1) suppression can decrease the expression of PD-L1 through the MEK/ERK and MYD88/TRAF6 pathways." (PMID 39343796, 2024).
adenoma (5 papers, 2010 to 2025). A neoplasm arising from the epithelium. "Combined TLR4/MyD88 expression analysis revealed significantly elevated scores (≥5) in CRC compared to adenoma cases (34.1% vs 12.2%, p<0.001)." (PMID 40703545, 2025). "TLR4 expression was significantly higher in CRC compared to adenomas (66.5% vs 30.5%, p<0.001), with MyD88 showing widespread expression in both groups (CRC: 97.2%, adenoma: 95.4%)." (PMID 40703545, 2025). "First, coordinated TLR4/MyD88 expression during adenoma-carcinoma progression remains poorly characterized." (PMID 40703545, 2025). "There are many reports have proved that MyD88 contributes to adenoma growth and progression and colon carcinogenesis." (PMID 38110638, 2023). "In this study, we performed a systematic immunohistochemical analysis of TLR4 and MyD88 expression in normal colon mucosae, adenomas, and CRC." (PMID 20145615, 2010). "So we could suggest more expression and/or activation of TLR-4/MyD88 in adenomas and adenocarcinomas." (PMID 26504896, 2015). "First, we demonstrated distinct expression patterns of TLR4/MyD88 between CRC and adenomas, characterized by significantly higher TLR4 expression in CRC tissues and predominant high-level MyD88 expression in CRC cases." (PMID 40703545, 2025). "The most striking finding was the significantly higher TLR4 expression in CRC tissues (66.5% vs 30.5%, p<0.001), while MyD88 showed widespread expression in both groups with comparable overall positivity rates (CRC: 97.2%, adenoma: 95.4%)." (PMID 40703545, 2025). "First, we demonstrated distinct expression patterns between CRC and adenomas, with significantly higher TLR4 expression and predominant high-level MyD88 expression in CRC tissues." (PMID 40703545, 2025). "Immunohistochemical expression analysis of TLR4 and MyD88: comparison between CRC and adenoma cases." (PMID 40703545, 2025). "MyD88 demonstrated widespread expression in both groups with comparable overall positivity rates (CRC: 97.2%, adenoma: 95.4%, p=0.518)." (PMID 40703545, 2025). "In this study, we observed that TLR4/MyD88 signalling was frequently overexpressed in CRC compared with normal mucosae and adenomas." (PMID 20145615, 2010). "Compared with normal mucosae and adenomas, 20% cancers displayed high expression of TLR4, and 23% cancers showed high expression of MyD88." (PMID 20145615, 2010). "The expression of TLR4 and MyD88 in 108 CRC samples, 15 adenomas, and 15 normal mucosae was evaluated by immunohistochemistry, and the correlations between their immunoscores and clinicopathological variables, including disease-free survival (DFS) and overall survival (OS), were analysed." (PMID 20145615, 2010). "Similar to that of TLR4, MyD88 expression was absent or very weak in normal mucosae, cancer margin samples, and adenomas." (PMID 20145615, 2010).
anemia (5 papers, 2018 to 2025). A reduction in the number of red blood cells, the amount of hemoglobin, and/or the volume of packed red blood cells. "Our results therefore suggest a novel mechanism by which gain-of-function somatic MyD88 mutations may interfere with iron re-utilization by sequestrating iron and hence, contribute to anemia in WM." (PMID 30234111, 2018).
B-cell neoplasm (5 papers, 2019 to 2024). A group of heterogeneous lymphoid tumors generally expressing one or more B-cell antigens or representing malignant transformations of B-lymphocytes. "Myeloid differentiation primary response protein 88 (MYD88) is a general adaptor protein, and MYD88 variants always drive the constitutive activation of nuclear factor-κB (NF-κB), which commonly occurs in various mature B-cell neoplasms (MBNs)." (PMID 37048750, 2023). "Interestingly, in two of the eight patients for whom a molecular profile was available, we found an MYD88 p.S219C mutation, which is rarely found in other B-cell neoplasms." (PMID 31590326, 2019). "Since leukemic MZL (mainly SMZL) is the mature B-cell neoplasm that most frequently displays a nonspecific phenotype, and up to 20% of such cases may present MYD88 L265P mutation, differential diagnosis with SMZL was made with special thoroughness." (PMID 37627180, 2023).
bacterial pneumonia (5 papers, 2013 to 2020). Acute infection of the lung parenchyma caused by bacteria (e.g., Streptococcus pneumoniae, Haemophilus influenzae, Chlamydia pneumoniae, Mycoplasma pneumoniae, and Legionella pneumophila). "One beneficial function of TLR4/MyD88-triggered MDSCs in the lung is to efferocytose apoptotic neutrophils to help resolve inflammation elicited during bacterial pneumonia." (PMID 24066282, 2013). "Similarly, global Myd88−/− mice were previously reported to show profound lung inflammation during late stage bacterial pneumonia in the presence of high bacterial loads." (PMID 25254554, 2014). "The downstream adaptor molecules [myeloid differentiation primary response protein 88 (MyD88) and Toll/IL-1R domain-containing adaptor-inducing IFN-β (TRIF)] of TLR signaling play crucial roles in bacterial pneumonia." (PMID 32849610, 2020). "Others have also found that absence of MyD88 results in unresolved pulmonary infiltrates following long-term radiation-induced lung injury, silica-induced fibrosis, and bacterial pneumonia." (PMID 32321514, 2020).